TFAP2C (transcription factor AP-2 gamma)
Diseases named in the same sentence as TFAP2C in open-access papers (continued):
Sharing a sentence is not in itself a finding about the gene and the disease.
lung carcinoma (15 papers, 2017 to 2025). "Many genes along the pathway, e.g., RAS and MAP 2 K1, were observed to be over-expressed in tumors in the three lung cancer data sets, confirming the downstream of tumor signals trigged by the abnormal TFAP2C-EGFR regulation." (PMID 33054712, 2020). "MiR-137 promotes lung cancer invasion and metastasis by suppressing transcription factor AP-2 gamma (TFAP2C)." (PMID 30813457, 2019). "For example, TFAP2C expression was elevated in lung carcinoma and high expression of TFAP2C promoted cell cycle activation and lung carcinoma cell tumorigenesis via by upregulating the oncogenic miR-183 and downregulating tumor-suppressive miRNA-33a." (PMID 29439714, 2018). "The TFAP2A and TFAP2C genes were reported to be involved in tumorigenesis as tumor suppressors in melanomas, breast, gastric, prostate, colorectal, and lung cancer." (PMID 36831334, 2023). "However, TFAP2A and TFAP2C is highly expressed in bladder cancer, lung cancer and other tumors, and overexpression of TFAP2A and TFAP2C is associated with poor prognosis of many tumors." (PMID 37859819, 2023). "Interestingly, although sharing TFAP2C expression, seminoma is much less malignant than breast and lung cancers, suggesting that additional factors counteract the role of TFAP2C in seminoma." (PMID 38123589, 2023). "Expression levels of TFAP2A and TFAP2C are higher in both adenocarcinoma and squamous cell lung cancer tissues than in normal lung tissues, and AP2 overexpression is associated with tumorigenesis and aggressive biology in lung cancer." (PMID 36123698, 2022). "We found that TFAP2C was highly expressed in lung cancer, prostate cancer, and BCa, among others." (PMID 36230734, 2022). "Based on the 93 TFBSs, we conducted TFAP2C siRNA knockdown experiments on lung cancer cell A549." (PMID 33054712, 2020). "To identify biomarkers for lung cancer development, we previously focused on the oncogenic roles of transcription factor TFAP2C in lung cancers and revealed the molecular mechanism of several oncogenes in lung tumorigenesis based on TFAP2C-related microarray analysis." (PMID 31296259, 2019). "Nonetheless, the TFAP2 genes family seems to play an important role in lung cancer pathogenesis, especially the TFAP2A, TFAP2C, and TFAP2D members in LUAD patients." (PMID 36831334, 2023). "Expression level of TFAP2C mRNA was positively correlated with tumor purity for both types of lung cancer—LUAD (p = 0.0304) and LUSC (p < 0.001)—which means that higher expression of TFAP2C gene is characteristic for tumor cells in both subtypes." (PMID 36831334, 2023). "A novel predicted transcription regulation between a TF TFAP2C and an oncogene EGFR was experimentally verified in lung cancer cells." (PMID 33054712, 2020). "We experimentally verified a novel predicted regulation, i.e., the regulation of TF TFAP2C on a hot once-gene EGFR, in lung cancer cell A549 and conceived a potential three TFBSs molecular mechanism." (PMID 33054712, 2020). "Different from E2F3 and TFAP2C, GRHL2 can suppress tumor metastasis by regulating of transcriptional activity of RhoG in lung cancer." (PMID 30967126, 2019). "In the lung carcinoma cell line (E114), DeepHistone recovered E2F3, TFAP2C and GRHL2." (PMID 30967126, 2019).
seminoma (14 papers, 2013 to 2025). A radiosensitive malignant germ cell tumor found in the testis (especially undescended), and extragonadal sites (anterior mediastinum and pineal gland). "To further explore the molecular mechanism underlying how TFAP2C promotes seminoma development, we performed RNA-seq profiling on the silenced group and control." (PMID 38123589, 2023). "For TFAP2C, the mRNA level was significantly up‐regulated in seminoma compared to non‐seminoma samples and this at least partly suggests that TFAP2C is associated with seminoma to some extent." (PMID 32857912, 2020). "Our study indicates that seminoma shares a more similar gene expression pattern with PGCs, and TFAP2C can promote the invasion and metastasis of tumor cells." (PMID 38123589, 2023). "Through differential gene expression analysis, we identified upregulated genes (n = 498) and downregulated genes (n = 843) upon TFAP2C silencing, indicating TFAP2C mainly act as a gene activator in seminoma." (PMID 38123589, 2023). "Given TFAP2C was identified as the top TFs specific to seminoma through both gene expression and chromatin accessibility analysis, we next sought to explore the functional impact of TFAP2C in seminoma." (PMID 38123589, 2023). "As expected, seminoma and PGCs shared specific expression of genes (C2) such as TFAP2C, POU5F1, NANOG and SOX17." (PMID 38123589, 2023). "Key transcription factors (TFs) such as TFAP2C, SOX17, OCT4/POU5F1 and NANOG are highly expressed in PGCs, and consequently are excellent diagnostic markers for seminoma and GCNIS14,18,19." (PMID 38123589, 2023). "We found that seminoma and PGCs display strong similarities in their transcriptomes, especially by sharing the expression of key TFs such as TFAP2C, POU5F1, NANOG and SOX17." (PMID 38123589, 2023). "We identify key gene expression programs share between seminoma and primordial germ cells, and further characterize the functions of TFAP2C in promoting tumor invasion and migration." (PMID 38123589, 2023). "This is in line with a recent study by Wei and collaborators, who demonstrated that METTL3 promotes resistance by introducing m6A in TFAP2C in the seminoma-like cell line TCam-2, both in vitro and in vivo." (PMID 34446080, 2021). "In seminoma, m6A methylation of TFAP2C mRNA initiated by METTL3, in conjunction with the other mechanisms, gives the tumour cells more time to develop resistance to CDDP treatment." (PMID 32857912, 2020). "To partially compensate for this deficiency, we leveraged The Cancer Genome Atlas (TCGA) database and studied the mRNA levels of METTL3 and TFAP2C in seminoma and non‐seminoma samples." (PMID 32857912, 2020). "Enhanced stability of TFAP2C mRNA promoted seminoma cell survival under cisplatin treatment burden probably through up‐regulation of DNA repair‐related genes." (PMID 32857912, 2020). "In the present study, enhanced stability of TFAP2C mRNA affected CDDP efficacy in seminoma TCam‐2 cells." (PMID 32857912, 2020). "Under in vitro differentiating conditons both, the parental and SOX2-deficient TCam-2 cells downregulated pluripotency/seminoma markers OCT3/4, TFAP2C, PRDM14 and PRAME, while SOX2 and DNMT3B expression remained low." (PMID 27283990, 2016). "Indeed, through studies using a seminoma cell line TCam-2, we proved that TFAP2C knockdown can lead to decreased cell invasion and migration." (PMID 38123589, 2023). "Here, given its close relationship with PGCs, seminoma clearly has a much easier route to obtain or maintain TFAP2C expression, which may explain its high occurrence in young adult men." (PMID 38123589, 2023). "We also found that the proliferation of seminoma was reduced in TFAP2C knockdown group." (PMID 38123589, 2023). "To further validate the protein expression levels of TFAP2C, we performed TFAP2C immunohistochemistry (IHC) staining using seminoma samples from four patients, and found high expression of TFAP2C in all the samples, which further proved the reliability of our findings." (PMID 38123589, 2023).
seminoma (continued). "Two molecules, methyltransferase‐like protein 3 (METTL3) and insulin‐like growth factor 2 mRNA‐binding protein 1 (IGF2BP1), were found to play crucial roles in potentiating resistance to CDDP through m6A methylation of transcription factor‐activating enhancer‐binding protein 2C (TFAP2C) in seminoma." (PMID 32857912, 2020). "Additionally, global 5mC levels remained unaffected and expression of seminoma-associated genes SOX17, PRAME, TFAP2C, PRDM1 and cKIT was maintained." (PMID 27283990, 2016). "Furthermore, expression of several markers was determined after siRNA mediated knockdown of TFAP2C in the human seminoma-like cell line TCam-2." (PMID 23967156, 2013). "Additionally, in seminoma, TFAP2C enhances resistance to cisplatin chemotherapy." (PMID 36230734, 2022). "Altogether, these results revealed the key role of TFAP2C in promoting migration and invasion by directly regulating genes such as FOSL1, LYPD3 and ITGA6 in the seminoma cell line, promoting further study to understand its role in seminoma tumorigenesis." (PMID 38123589, 2023). "Collectively, we showed the interactions of the METTL3/IGF2BP1/TFAP2C signalling pathway and unveiled its contributions to in vivo CDDP resistance in seminoma." (PMID 32857912, 2020). "At least based on our findings, m6A of TFAP2C promotes TCam‐2 cell survival and confers resistance to CDDP in seminoma." (PMID 32857912, 2020). "Both WEE1 and BRCA1 showed higher expression in seminoma compared to non‐seminoma samples according to the TCGA database, and the expression of BRCA1 was significantly correlated with TFAP2C." (PMID 32857912, 2020). "TCam-2 cells express typical primordial germ cell and GCNIS marker genes (SOX17, PRAME, cKIT, TFAP2C, PRDM1/BLIMP1) and show a typical GCNIS/seminoma morphology (big roundish cells with a big nucleus and clear cytoplasm)." (PMID 31130628, 2019). "Pluripotency and seminoma markers like NANOG, OCT3/4, LIN28, TFAP2C, cKIT, D2-40 and PRDM1 were downregulated." (PMID 27283990, 2016). "Most importantly, the majority of TCam-2-ΔSOX2 cells maintains a seminoma-like cell fate for at least 6 weeks in vivo, indicated by a typical seminoma-like morphology and expression of seminoma markers SOX17, PRAME, TFAP2C and PRDM1 (nuclear)." (PMID 27283990, 2016). "Analyses of these cells revealed downregulation of the pluripotency and seminoma markers OCT3/4, SOX17, PRDM1 and TFAP2C." (PMID 27283990, 2016). "TSPO protein expression was assessed in paraffin sections from several seminoma cases, in parallel with pluripotency genes OCT3/4 (OCT4; POU5F1) and AP2γ (TFAP2C), considered as seminoma markers." (PMID 27608010, 2016). "In TCam-2-ΔSOX2 clones, expression of seminoma markers SOX17, PRAME, TFAP2C, LIN28 and PRDM1 was slightly downregulated or remained unchanged compared to the TCam-2 in vitro cells." (PMID 27283990, 2016). "PRDM1, the transcription factor TFAP2C and SOX17 render the PGCs and seminomas in a state of dormant pluripotency, meaning that they express pluripotency markers, but are not able to induce differentiation into somatic tissues." (PMID 26226633, 2015). "TFAP2c, the transcription factor AP-2 family member, was methylated by METTL3 and recognized by IGF2BP1, which enhances the mRNA stability of TFAP2c, thereby making seminoma resistant to cisplatin." (PMID 40180937, 2025). "We found TFAP2C and SOX17 also highly expressed within the areas of seminoma in the spatial data." (PMID 38123589, 2023). "For example, methyltransferase‐like 3 (METTL3) could stabilise the transcription factor AP‐2 gamma (TFAP2C) mRNA in an insulin‐like growth factor 2 mRNA binding protein 1 (IGF2BP1)‐dependent mode and further enhance cisplatin resistance in seminoma." (PMID 35696608, 2022). "TFAP2C promotes TCam-2 cell survival and confers resistance to CDDP in seminoma." (PMID 34124065, 2021).
seminoma (continued). "Besides, we found that two DNA repair‐related genes were up‐regulated in the CDDP treatment context and were correlated with m6A methylation of TFAP2C, indicating the contribution of the DNA repair mechanism in cellular resistance to CDDP in seminoma." (PMID 32857912, 2020). "Additionally, strong and comparable expression of the seminoma and pluripotency markers OCT3/4, NANOG, LIN28, SOX17, PRAME, PRDM1/BLIMP1 and TFAP2C was found in TCam-2, TCam-2-ΔSOX2 and TCam-2-ΔSOX2/FOXA2 cells." (PMID 31130628, 2019). "Although the vast majority of cells stained positive for the seminoma markers SOX17, OCT3/4 and TFAP2C, small areas displayed absence of staining of these pluripotency- and seminoma-related genes, pointing at a heterogeneity of the tumor tissues (red arrows)." (PMID 27283990, 2016). "We postulate that the small subpopulation of OCT3/4/SOX17/TFAP2C negative cells is highly similar to in vitro differentiated TCam-2 and thus resembles a mixed non-seminoma in vivo." (PMID 27283990, 2016). "Furthermore, high levels of TFAP2C protein were observed in precursor lesions of GCC (carcinoma in situ (CIS)) and classical seminomas." (PMID 23967156, 2013). "Expression of typical seminoma markers (PRDM1/BLIMP1, SOX17, PRAME, TFAP2C) was also detectable in TCam-2-ΔSOX2/FOXA2 tumor tissues, in contrast to EC reprogramming factors (GDF3, DPPA3, DNMT3B, GAL), which could only be detected in 2102EP in vivo or reprogrammed TCam-2 cells." (PMID 31130628, 2019). "Furthermore, additional EC and pluripotency genes were upregulated (SOX2, LEFTY1 /2, DNMT3L, SALL4, DPPA5, BCAT1, FZD7, LIN28, ZIC3), while seminoma-associated genes where downregulated (SOX17, TFAP2C, cKIT, PRAME), without changing 5mC-levels." (PMID 26226633, 2015). "Notably, TFAP2C and POU5F1 were highly enriched in seminoma, re-enforcing our findings based on scRNA-seq that these key TFs may play an important role in seminoma." (PMID 38123589, 2023). "However, with downregulation of PGC- (PRDM1, TFAP2C, cKIT) and pluripotency (NANOG, OCT3/4, LIN28) marker genes, persisting SOX17 expression together with activation of the Hippo pathway resulted in differentiation into a mixed non-seminoma with predominant choriocarcinoma-like components." (PMID 26226633, 2015). "Owing to the difficulty in obtaining samples from CDDP‐resistant seminoma cases, we were not able to detect the expressions of METTL3 and TFAP2C in clinical chemo‐resistant samples." (PMID 32857912, 2020). "Furthermore, TCam-2-ΔSOX2/FOXA2 derived tumors stained positive for pluripotency and seminoma markers OCT3/4, SOX17, TFAP2C, and PRDM1/BLIMP1, but were negative for the differentiation-markers AFP and EOMES." (PMID 31130628, 2019).
bladder cancer (10 papers, 2019 to 2025). "In bladder cancer, TFAP2C transcriptionally increases prostate cancer associated transcript 1 (PCAT1) expression, which physically interacts with c-Myc to transcriptionally activate SLC7A11 expression." (PMID 37291585, 2023). "For TFAP2C, in bladder cancer, TFAP2C expression is elevated, which is associated with enhanced malignancy and cisplatin resistance." (PMID 37291585, 2023). "Bioinformatics analyses in bladder cancer patients found high expression of TFAP2C gene to be associated with an enhancement of adverse processes related to cancer progression, probably due to its oncogenic nature." (PMID 33691672, 2021). "However, while the role of the Transcription Factor AP-2 Gamma (TFAP2C) gene (encoding AP-2γ) in bladder cancer and various other cancer types currently appears unequivocal, the role(s) of the TFAP2A gene (encoding AP-2α) is uncertain." (PMID 33718178, 2021). "In the context of cisplatin resistance, TFAP2C modulates chemotherapy sensitivity in bladder cancer cells." (PMID 40541807, 2025). "The trend of survival curve of TFAP2A, TFAP2B and TFAP2C in bladder cancer was basically consistent with that of GEPIA." (PMID 37859819, 2023). "We analyzed the relationship between TFAP2 family proteins and the clinical stage of bladder cancer patients, and found that TFAP2C protein was positively correlated with the worse clinical stage of patients, while TFAP2B showed the opposite trend." (PMID 37859819, 2023). "Immunohistochemical results from HPA database showed that the expression of TFAP2A, TFAP2B and TFAP2C in clinical samples of bladder cancer patients was higher than that in normal tissues." (PMID 37859819, 2023). "TFAP2C is also implicated in docetaxel resistance by promoting the cell cycle in ESCC and by inhibiting ferroptosis in bladder cancer." (PMID 37291585, 2023). "The survival analysis of TFAP2 family genes by GEPIA database showed that TFAP2A, TFAP2B and TFAP2C were significantly related to the survival and prognosis of bladder cancer patients." (PMID 37859819, 2023). "TFAP2C is elevated in bladder cancer and testicular germ cell tumor to mediate cisplatin resistance and increase malignancy." (PMID 37291585, 2023). "Investigating whether TFAP2C inhibition can sensitize resistant bladder cancer cells to other treatments, such as immunotherapy or targeted therapies, could provide valuable insights." (PMID 40541807, 2025). "While previous research focused on the downstream effects of YAP and β-catenin, this study elucidates a novel mechanism involving TFAP2C's role in regulating these pathways, representing a significant progression in understanding cisplatin resistance in bladder cancer." (PMID 40541807, 2025). "Transcription factor AP-2 gamma (TFAP2C) plays a pivotal role in bladder cancer progression." (PMID 40541807, 2025). "We used SMART database to analyze the methylation of different TFAP2 family in patients with BLCA, and found that the methylation of TFAP2A, TFAP2B, TFAP2D and TFAP2E in bladder cancer tissues was significantly higher than that in adjacent tissues, while TFAP2C showed the opposite trend." (PMID 37859819, 2023). "However, our study shows that the expression of TFAP2C is positively correlated with the clinical stage of bladder cancer, and patients with high expression of TFAP2C have a shorter survival period." (PMID 37859819, 2023). "However, the specific mechanism by which TFAP2C transcriptionally activates Yes-associated protein (YAP) to promote cisplatin resistance in bladder cancer has not been previously reported, highlighting an innovative area for future research." (PMID 40541807, 2025). "In bladder cancer, in cooperation with PPARɣ inactivation and other transcription factors, TFAP2A and TFAP2C overexpression induced the shift from the luminal subtype to the basal-squamous transition during tumor progression." (PMID 37291585, 2023).